TREX1 (three prime repair exonuclease 1)
Diseases named in the same sentence as TREX1 in open-access papers (continued):
Sharing a sentence is not in itself a finding about the gene and the disease.
systemic lupus erythematosus (continued). "In human, loss-of-function mutations in TREX1 trigger autoimmune diseases, such as Aicardi–Goutières syndrome (AGS), systemic lupus erythematosus (SLE), familial chilblain lupus (FCL), and retinal vasculopathy with cerebral leukodystrophy (RVCL)." (PMID 34659260, 2021). "Mutations in TREX1 have been associated with a broad spectrum of autoimmune and inflammatory phenotypes, including Aicardi-Goutières syndrome (AGS), familial chilblain lupus (FCL), systemic lupus erythematosus (SLE), and retinal vasculopathy with cerebral leukodystrophy (RVCL)." (PMID 28297665, 2017). "Biallelic TREX1 T303P variant causes AGS, whereas three monoallelic missense variants (P290L, Y305C, G306A) seem to increase the risk for systemic lupus erythematosus (SLE)." (PMID 40072623, 2025). "Mutations in TREX1 are associated with the development of several autoimmune diseases, including Aicardi-Goutières Syndrome (AGS), systemic lupus erythematosus (SLE), familial chilblain lupus (FCL), and retinal vasculopathy with cerebral leukodystrophy (RVCL)." (PMID 38166933, 2024). "Mutations in TREX1 in humans are associated with the autoimmune and autoinflammatory disorders Aicardi-Goutières syndrome (AGS), familial chilblain lupus (FCL), systemic lupus erythematosus (SLE), and retinal vasculopathy with cerebral leukodystrophy (RVCL)." (PMID 24817865, 2014). "The 3' - 5' DNA exonuclease, TREX1, is a negative regulator of the type I interferon response, while TREX1 variants are considered to confer risk for non-monogenic systemic lupus erythematosus (SLE)." (PMID 41593088, 2026). "There are four heritable TREX1-related disorders: Aicardi–Goutières Syndrome type 1 (AGS1—OMIM #225750), Familial Chilblain Lupus (FCL—OMIM #610448), Systemic Lupus Erythematosus (SLE—OMIM #152700), and Retinal Vasculopathy with Cerebral Leukodystrophy (RVCL—OMIM #192315)." (PMID 35885962, 2022). "Moreover, Trex1 deficiency resulted in the hyperproduction of type I IFNs and proinflammatory cytokines and have been associated with autoimmune disorders, such as Aicardi‐Goutieres syndrome (AGS) and systemic lupus erythematosus (SLE)." (PMID 33511009, 2021). "Dysfunction of TREX1 leads to accumulation of cytosolic nucleic acids and a range of autoimmune diseases, such as Aicardi–Goutières syndrome (AGS), systemic lupus erythematosus (SLE), retinal vasculopathy, cerebral leukodystrophy and familial chilblain lupus (FCL)." (PMID 37870446, 2023).
autoimmune disease (73 papers, 2011 to 2026). A disorder resulting from loss of function or tissue destruction of an organ or multiple organs, arising from humoral or cellular immune responses of the individual to their own tissue constituents. "The significance of TREX1 in the regulation of immune response and the effects of its deficiencies on autoimmune disorders have been well documented." (PMID 40581636, 2025). "While the effects of germline inactivating mutations on TREX1 protein structure, function, and autoimmune disease have been extensively documented, understanding of the effects of TREX1 variants in cancer is only now emerging." (PMID 40581636, 2025). "We modeled human TREX1 variants occurring in autoimmune disease and cancer samples at 12 protein positions to evaluate their predicted impact on protein stability and function." (PMID 40581636, 2025). "Mutation of TREX1 in autoimmune diseases, dissociating TREX1 from the endoplasmic reticulum, disrupts the localization of TREX1 in micronuclei, reduces micronucleus-damaged DNA degradation, and enhances cGAS activation." (PMID 39759116, 2025). "We demonstrated that cDCs drive disease phenotypes during TREX1 deficiency in this study, but pDCs were also suggested to contribute to other autoimmune diseases such as SLE." (PMID 39254994, 2024). "TREX1, as a DNA-degrading enzyme, is closely associated with DNA-sensing mediated innate immune signaling and development of several autoimmune diseases." (PMID 38166933, 2024). "Our study suggests that inhibition of cGAS in one specific cell type, cDCs, will be sufficient to ameliorate autoimmune diseases caused by Trex1 deficiency." (PMID 39254994, 2024). "Mutations in TREX1 cause autoimmune disorders, including Aicardi–Goutieres syndrome type 1, systemic lupus erythematosus, chilblain lupus, and retinal vasculopathy with cerebral leukodystrophy." (PMID 38714348, 2024). "Previous works have revealed that TREX1 deficiency is implicated in the development of several autoimmune diseases, mechanistically through the sustained activation of type I IFN pathway induced by aberrant accumulation of DNA." (PMID 38166933, 2024). "Mutations in TREX1 lead to protein inactivation, resulting in excess interferon-1, leading to autoimmune disease." (PMID 36814213, 2023). "Mutations in TREX1 and RNase H2 were shown to lead to very similar autoimmune diseases, suggesting that they function in the same pathway and share common DNA/RNA hybrid substrates derived from endogenous retroelements." (PMID 37870446, 2023). "Three-prime repair exonuclease 1 (TREX1) dysfunction has been suggested to be associated with autoimmune diseases and inflammation." (PMID 37163421, 2023). "It has been suggested that cGAS pathway activation is the key signaling for autoimmunity diseases caused by a TREX1 missense mutation." (PMID 37834184, 2023). "Loss-of-function mutations of TREX1 have been identified in human patients with autoimmune disorders such as Aicardi-Goutières syndrome (AGS) and lupus-like autoimmune disorders." (PMID 37834184, 2023). "We further find that MXC significantly dampens the expression levels of interferon-stimulated genes (ISGs) by using DNA 3’ repair exonuclease 1 (TREX1)-deficient cell, an experimental model for self-DNA-induced autoimmune disease." (PMID 37120570, 2023). "Together, these results highlight how structures of hTREX1 advance understanding of TREX1 biochemical function and human TREX1-associated autoimmune disease." (PMID 35879334, 2022). "Structures of human TREX1 and the human TREX1–DNA complex allow analysis of mutations associated with autoimmune disease and define 22 mutation sites predicted to directly impact human TREX1 function." (PMID 35879334, 2022). "Here the authors determine the first structure of the human TREX1–DNA complex, and provide a new foundation to explain how patient TREX1 mutations cause autoimmune disease." (PMID 35879334, 2022).
autoimmune disease (continued). "Mutations in human TREX1 have been linked to a broad spectrum of autoimmune diseases, including Aicardi-Goutieres syndrome, familial chilblain lupus, systemic lupus erythaematosus, and retinal vasculopathy." (PMID 34997539, 2022). "TREX1 is a cytosolic DNA nuclease and the genetic mutations of it are linked to autoimmune diseases." (PMID 35879334, 2022). "The structure of human TREX1 additionally enables direct analysis of the relationship between TREX1 mutations and autoimmune disease." (PMID 35879334, 2022). "We map each TREX1 mutation associated with autoimmune disease and establish distinct categories of substitutions predicted to impact enzymatic function, protein stability, and interaction with cGAS-DNA liquid droplets." (PMID 35879334, 2022). "There is a causal relationship between TREX1 genetic variants and multiple mechanisms of TREX1 enzyme dysfunction that have now been linked to a spectrum of autoimmune diseases in humans." (PMID 33868310, 2021). "Loss-of-function mutations in Trex1 have been identified in autoimmune disorders such as Aicardi–Goutières syndrome (AGS) and familial chilblain lupus in human patients." (PMID 33968056, 2021). "The abnormal activation of cGAS in autoimmune diseases caused by incomplete self-DNA clearance has also been demonstrated in Trex1−/− and DNaseII−/− mice." (PMID 32180716, 2020). "Loss-of-function mutations of TREX1 result in the accumulation of self-DNA and autoimmune diseases, such as SLE." (PMID 31440232, 2019). "The role of TREX1 531C>T polymorphism in the development of autoimmune diseases is not yet well understood." (PMID 31861565, 2019). "It was also suggested that DNA/RNA hybrids are potential targets of TREX1, since the deficiencies of TREX1 demonstrate similar features of autoimmune diseases as those of RNase H2 that was known for processing the hybrid substrates." (PMID 29734329, 2018). "Aicardi-Goutières syndrome (AGS) is one of the IFN-associated autoimmune diseases caused by mutation of the TREX1 gene." (PMID 28771599, 2017). "Autoimmune diseases caused by TREX1 mutations can be rescued by functional deficiency of IRF3 or type I IFN receptor (IFNR)." (PMID 28771599, 2017). "Autoimmune diseases like AGS are clearly linked to nucleic acid metabolism since mutations in TREX1, RNASEH2A-2C, SAMHD1, ADAR1, or IFIH1 predispose individuals to disease (12, 48, –, 51)." (PMID 28679751, 2017). "On these bases, we decided to investigate the role of TREX1 gene in susceptibility to three different autoimmune diseases in the Italian population: SLE, SS, and systemic sclerosis (SSc)." (PMID 24224166, 2013). "Mice which lack either of two enzymes responsible for degradation of DNA, 3′ repair exonuclease 1 (Trex1) and DNaseII, develop spontaneous autoimmune disorders associated with the initiation of IRF-3-dependent cytosolic DNA sensing." (PMID 23251783, 2012). "As PRRs do not sufficiently differentiate between exogenous and endogenous nucleic acids, TREX1 deficiency may trigger chronic inflammatory and autoimmune diseases." (PMID 39766901, 2024). "Also, it displays promising therapeutic effects on inflammation and autoimmune diseases, such as alleviating inflammatory phenotypes in Trex1 deficient mice." (PMID 39558862, 2024). "cGAS is required for lethal autoimmune disease in the Trex1-deficient mouse model of AGS." (PMID 37834184, 2023). "All previous structural understanding of TREX1 function is derived from crystal structures of mTREX122–27,30, limiting analysis of human-specific substitutions and the effects of patient mutations associated with autoimmune disease." (PMID 35879334, 2022). "Autoimmune disease-associated TREX1 mutations in surface-exposed residues (e.g., E198K, K66R, P132A, A223T) may also alter binding to protein partners, post-translational modifications, and interaction with cGAS-DNA condensates." (PMID 35879334, 2022).
autoimmune disease (continued). "In addition to association with autoimmune disease, recently reported links between TREX1 dysregulation and cancer suggest inhibition of TREX1 exonuclease activity is a promising target for cancer immunotherapy." (PMID 35879334, 2022). "Depletion of STING, IRF3, cGAS, or IFN-I receptor in TREX1-deficient mice protects against autoimmune disorders and death, indicating that cGAS–STING–IRF3 axis-regulated IFN-I production is responsible for autoimmune disorder development in TREX1-deficient mice." (PMID 31440232, 2019). "Moreover, the D272fs and V235fs mutations usually affect the DNase-independent roles of TREX1 and trigger serologic autoimmunity, which likely contributes to the development of autoimmune disease." (PMID 31440232, 2019). "Thus, large genetic studies have identified low frequency variants with relevant functional significance associated with autoimmune diseases (e.g. TREX1 in SLE25 and TYK2 in several autoimmune diseases)." (PMID 29844438, 2018). "Notably, C-terminal deletion mutations that impede ER targeting of TREX1 cause the autoimmune disorders RVCL and SLE7, 8 underpinning a pivotal role of the subcellular localization of TREX1." (PMID 27230542, 2016). "NASPs may also play an important role in treating autoimmune disorders caused by deficiencies in nucleases such as DNase, RNase and Trex1." (PMID 23936008, 2013). "In conclusion, this study contributes to the demonstration that TREX1 is involved in autoimmune diseases and proposes that the spectrum of involved autoimmune diseases can be broader, since we detected a previously unreported possible association between TREX1 mutations and SSc." (PMID 24224166, 2013). "Whereas some germline TREX1 variants may have pathogenic effects in autoimmune disorders, some of the same functional variants may provide a therapeutic vulnerability in cancer treatment by dampening or abrogating TREX1 activity and increasing antitumor immune response." (PMID 40581636, 2025). "While TREX1 protein sequence variants and copy number alterations are present in many cancer histologies, their impact on malignancy may differ from functional effects in autoimmune disorders." (PMID 40581636, 2025). "In addition, A151 was also able to inhibit the production of IFN‐I in TREX1‐deficient cells, raising the possibility that A151 may be used for the treatment of dsDNA‐mediated autoimmune diseases." (PMID 38525112, 2024). "It was demonstrated that cGAS activation causes autoimmune diseases in Trex1-/- and DNaseII-/- mice, suggesting that inhibiting cGAS could prevent and treat some human autoimmune diseases triggered by self-DNA; and tonic prime-boost of STING signaling mediates Niemann–Pick disease type C." (PMID 38999073, 2024). "We also demonstrated that it can report TREX1 deficiency (Fig. EV5), which associated with several autoimmune diseases." (PMID 39984755, 2025). "TREX1 prevents the accumulation of dsDNA as an autoantigen to induce autoimmune diseases by cleaving it." (PMID 39759116, 2025). "However, due to intertwined effects of TREX1 on both the tumor and the immune system, the role of its variants in cancer may be complex, as some germline TREX1 variants have been associated with hematological malignancies in patients with autoimmune diseases." (PMID 40581636, 2025). "Research has demonstrated that TREX1 deficiency has a close association with various autoimmune diseases (e.g., AGS, SLE) and that in TREX1-deficient mouse models, deletion of cGAS or STING can ameliorate these disease phenotypes." (PMID 39737190, 2024). "Overall, these results demonstrate that TREX1 PPII mutations, including P61Q, impair proper immune regulation and lead to autoimmune disease through TREX1 destabilization." (PMID 38260344, 2024). "In various autoimmune diseases, dysfunctional TREX1 leads to accumulation of endogenous ssDNA, dsDNA, and DNA/RNA hybrids in the cytoplasm and triggers immune activation." (PMID 38714348, 2024).
autoimmune disease (continued). "Altogether, these results demonstrated that XQ2B efficiently attenuated systemic inflammation in Trex1-/- mice, highlighting the therapeutic potential of cGAS-specific inhibitors targeting protein-DNA interface in cGAS-related autoimmune diseases." (PMID 37783727, 2023). "In Trex1-KO mice, SN-011 was well tolerated, potently suppressed features of inflammatory and autoimmune diseases, and prevented mortality." (PMID 37354378, 2023). "With wild-type C57BL/6 mice as the control, we observed the ameliorative effect of Glab (40 mg/kg) on autoimmune diseases in Trex1−/− mice by daily intraperitoneal injection." (PMID 38066431, 2023). "Dysfunctional TREX1 was also observed in the immune system activation of autoimmune diseases through the accumulation of DNA/RNA hybrids, i.e. they are potentially TREX1 substrates." (PMID 37870446, 2023). "In turn, a second-generation compound 9 was obtained and the potential for this type of compounds in therapy of autoimmune diseases such as AGS or SLE was validated in the AGS model TREX1-/- mice." (PMID 36172373, 2022). "For instance, inhibitors targeting cGAS significantly downregulated IFN expression in TREX1-/- PMBCs in AGS model mice, showing excellent potential for drug development in the treatment of autoimmune diseases caused by DNA accumulation such as AGS and SLE." (PMID 36172373, 2022). "Deletion of Cgas is sufficient to suppress the autoimmune disease phenotype in the Trex1−/− mouse model of AGS." (PMID 33968056, 2021). "Previous studies have reported that Three-prime repair exonuclease 1(TREX1), an endogenous DNA exonuclease, prevents immune activation by depleting damaged DNA, thus preventing the development of certain autoimmune diseases." (PMID 28334850, 2017). "However, although the role of TREX1 is well characterized in autoimmune diseases, its potential contribution to antitumor immunity and chemoresistance is poorly understood." (PMID 39177280, 2024). "Glabridin and Licochalcone B, as the main active ingredients in licorice, showed promising ameliorative effects on autoimmune diseases contributed to Trex1 knockout, and their mechanism of action may be related to affecting the binding of IRF3 with STING." (PMID 38904004, 2024). "The three-prime repair exonuclease 1 (TREX1) protein is a sensor that promotes the degradation of DNA dispersed in the cytoplasm (ssDNA and dsDNA), both of endogenous and exogenous origin, contributing to the prevention of autoimmune diseases." (PMID 38675842, 2024). "In various autoimmune diseases, dysfunctional TREX1 (Three prime Repair Exonuclease 1) leads to accumulation of endogenous single-stranded DNA (ssDNA), double-stranded DNA (dsDNA) and DNA/RNA hybrids in the cytoplasm and triggers immune activation through the cGAS–STING pathway." (PMID 37870446, 2023). "Additionally, palbociclib ameliorates autoimmune disease features induced in dextran sodium sulfate (DSS) or Trex1-KO mice." (PMID 37354378, 2023). "Trex1 is a very important endogenous DNA nucleic acid exonuclease in cells that can remove DNA fragments that need to be processed by hydrolyzing damaged DNA in damaged cells, thus avoiding immune hyperactivation and autoimmune diseases." (PMID 38066431, 2023). "Another in vivo study has proved that genetic deletion of Trex1 or DNase II could lead to lethal autoimmune diseases in mice." (PMID 37834184, 2023). "Frequently, these autoimmune diseases are the result of mutations that inactivate a negative-regulator of cGAS-STING signaling named three-prime repair exonuclease 1 (TREX1)." (PMID 35879334, 2022). "Meanwhile, the tested results in other signaling pathways showed that compound 2 was a selective inhibitor of cGAS and reduced the mRNA level of IFN-β in bone marrow derived macrophages (BMDM) of AGS model TREX1-/- mice, thus indicating the potential for the treatment of autoimmune diseases." (PMID 36172373, 2022).